SPP1 (secreted phosphoprotein 1)
Diseases named in the same sentence as SPP1 in open-access papers (continued):
Sharing a sentence is not in itself a finding about the gene and the disease.
tumor (continued). "Furthermore, CgA, rather than SPP1, serves as an indicator of tumor aggressiveness." (PMID 38835066, 2024). "Given that in clinical practice, although both occurred in the liver, we have clearly found that HCC has an out better blood supply than ICC, it is speculated that FOLR2+ TAM lacks this oxygen competition phenomenon with HCC tumor cells, without the phenotype transformation to SPP1+ macrophages." (PMID 39716897, 2024). "We further evaluate whether the positive frequency of autoantibody to SPP1 had significant differences in different clinical subgroups from ESCC (age, sex, smoking, drinking, lymphatic metastasis, TNM stage, distance metastasis, differentiation, family tumor history)." (PMID 36038839, 2022). "Also, due to the small number of S100P + SPP1 + and S100P-SPP1− cells in scRNA-seq data, we could not evaluate the molecular characteristics of these two types of tumor cells at the single-cell level accurately." (PMID 35347134, 2022). "We found significantly decreased levels of Afp (a marker of undifferentiated HCC), Spp1, Gpc3 (markers of early HCC), and Epcam (a marker of stemness), suggesting that Myc-R26Met tumours might be more differentiated and at more advanced stages than Alb-R26Met tumours." (PMID 36433941, 2022). "Furthermore, tumor cells seeded in a low concentration of collagen gels acquired TIC-like phenotypes and revealed enhanced resistance to chemotherapeutic agents, which was dependent on an integrin β1 (ITGB1)/Y-box Binding Protein 1 (YBX1)/Secreted Phosphoprotein 1 (SPP1)/NF-κB signaling pathway." (PMID 34758833, 2021). "In contrast, in normal tissue, there were few SPP1+ macrophages surrounding FAP+ fibroblasts, indicating that the interactivity between them primarily occurs within tumor tissues rather than in normal tissues." (PMID 40438108, 2025). "Their work revealed that SPP1-mediated ECM remodeling promotes collagen VI (COL6A3) and decorin (DCN) deposition, creating a fibrotic tumor microenvironment that physically excludes cytotoxic T lymphocytes (CTLs) and contributes to immune evasion." (PMID 41293726, 2025). "Another study demonstrated that in the TME of ICI-nonresponsive NSCLC patients, SPP1+macrophages and COL11A1+ fibroblasts form highly enriched cellular networks that suppress T cells infiltration into the tumor parenchyma via intercellular interactions." (PMID 41268560, 2025). "Tumor samples consistently exhibited elevated expression levels of SFN, SPP1, and NDRG1 genes, regardless of being paired or unpaired, in comparison to non-tumor samples." (PMID 39066845, 2024). "Recent research suggested that tumor macrophage polarity, characterized by CXCL9 and SPP1 expression rather than traditional M1 and M2 markers, exhibits a significantly strong prognostic correlation in HNSCC." (PMID 38962427, 2024). "Observing that CD8+ MAITs, rather than other CD8+ T cells or NK cells, infiltrate the tumor's leading edge, we identified a potential mechanism wherein CD8+ MAIT cells recruit SPP1+ macrophages into the TME via the CCL5‐CCR1 or CSF1‐CSF1R axis." (PMID 39716897, 2024). "SPP1 is a known negative prognostic marker in HNSCC and appears to be predominantly expressed in macrophages and to a much smaller extent in tumor cells in HNSCC." (PMID 37835599, 2023). "Interestingly, they found that tumor SPP1 expression, as measured by IHC, is not correlated with plasma SPP1 level and patient outcome, and they hypothesized that non-malignant cells may contribute to plasma SPP1 concentrations." (PMID 37190178, 2023). "Pleural and tumor levels of MPE-related proinflammatory mediators (IL-6; VEGF; monocyte chemoattractant protein-1, MCP-1; TNFA; secreted phosphoprotein 1, OPN; and macrophage inflammatory protein 2, MIP2) were not affected by macrophage CSF1R ablation." (PMID 35315360, 2022).
tumor (continued). "According to the clustering results, C1q+ TAMs, SPP1+ TAMs, and CCL20+IL1B+ macrophages were substantially more abundant in tumor tissue than in non-malignant colorectal tissues." (PMID 36172359, 2022). "While physical interactions among LGALS9-SLC1A5 and SPP1-PTGER4 pairs have been described in the curated database of CellPhoneDB32, a functional consequence of these interactions between tumor cells and TAM has not been determined." (PMID 36476645, 2022). "Furthermore, the SPP1/CD44-mediated crosstalk between SPP1+ macrophages and cancer cells in the SPP1+ macrophage-enriched region formed a specific niche to accelerate the malignant progression of GC, which means that the architecture of intratumor heterogeneity may evolve with tumor progression." (PMID 36612160, 2022). "The proportion of SPP1+C1QC-/SPP1+C1QC+ TAMs but not SPP1-C1QC+/SPP1-C1QC- TAMs significantly increased from normal to adjacent/tumor samples among different cancer types, suggesting the potential role of SPP1+ TAMs in tumorigenesis and tumor metabolism." (PMID 36333338, 2022). "In addition, independent of tumor stage, overexpression of LEF1, not SPP1, denotes a poor prognosis for survival." (PMID 21383983, 2011). "Thus, changes in Gast, Ccla3, Glycam1, Spp1, Serpina1a, Cela1, Cldn2, and Fabp2 are a result of GW501516 treatment and are not tumor specific." (PMID 21318167, 2010). "In this study, we investigated the differences in gene expression between normal tissues and tumor tissues, as well as TACE response and non-response groups, and intersected them with MRGs, successfully identifying four key genes (CDC20, LPCAT1, PON1, and SPP1)." (PMID 40404896, 2025). "Secreted cytokines (MIF/CSF1) mainly target C1QC+TAMs to impede the antitumor immune effects of TAMs rather than those of SPP1+TAMs, suggesting that anti-CSF or MIF treatments may be insufficient to deplete macrophage subgroups with tumor growth-promoting potential." (PMID 39323622, 2024). "Moreover, the molecular mechanisms responsible for the correlation between OCT4 and SPP1 in cancer cells was not elucidated; therefore, future work should focus on investigating the roles of OCT4A and SPP1C in tumour cell migration, as well as in other biological activities." (PMID 32503462, 2020). "Moreover,−443 C was also found to be associated with more severe inflammatory disease and rapider tumor progression and metastasis, which was not consistent with the manifestation in DMD patients treated with GCs, suggesting that GCs might be a critical factor in the regulation of SPP1." (PMID 32849198, 2020).
cancer (961 papers, 2004 to 2026). A tumor composed of atypical neoplastic, often pleomorphic cells that invade other tissues. "This study investigates the role of extracellular matrix cancer-associated fibroblasts (eCAFs) and their interaction with SPP1+ macrophages in LUAD progression and prognosis." (PMID 40657391, 2025). "SPP1+ macrophages have been implicated in a wide range of diseases beyond cancer, particularly those involving lipid metabolism and fibrosis." (PMID 40395129, 2025). "Our study, however, observed upregulation of SPP1 in senescent T cells and cancer cells from BM, characterizing the association of the ligand‐receptor axes of the SPP1 pathway with senescence, immunosuppression and angiogenesis in BM of NSCLC patients." (PMID 39231761, 2025). "Increased SPP1 levels are associated with greater cell adhesion, migration, and invasion, suggesting its role in cancer spread." (PMID 41391064, 2025). "It has been previously shown that activation of the CSF-1/CSF-1R signaling pathway and overexpression of CSF-1R promote PC progression and increase the expression of the SPP1 transcript encoding osteopontin, a key factor in cancer development and metastasis." (PMID 39941714, 2025). "There has also been a significant interest in the association between SPP1 and reduced immunity in several diseases including cancer in humans." (PMID 39857756, 2025). "In liver cancer, for instance, resident Kupffer cells can transition into liver metastasis‐associated macrophages (LMAMs) with high SPP1 expression, driving cancer stemness through vitronectin and CCL15 signaling pathways." (PMID 40047497, 2025). "SPP1 is associated with various cancers, cardiovascular diseases, respiratory diseases, and kidney diseases." (PMID 41293726, 2025). "A high abundance of these SPP1-expressing TAMs, along with cancer-associated fibroblasts (CAFs), has been closely associated with resistance to immunotherapy." (PMID 39727934, 2024). "Due to cell adhesion, SPP1 expression is closely related to tumorigenesis and metastasis, suggesting that it can be used as a diagnostic and prognostic biomarker of cancer." (PMID 38415922, 2024). "SPP1 is associated with cancer stemness and is capable of driving cancer progression and metastasis." (PMID 39033089, 2024). "Prior research indicated that the SPP1 protein secreted by cancer-associated fibroblasts augmented drug resistance by activating the PI3K/AKT/mTOR signaling pathway through integrin-mediated PKCα phosphorylation." (PMID 39066845, 2024). "In these tumors, a histological barrier formed by the interaction of cancer-associated fibroblasts (CAFs) and SPP1+ macrophages decreases immunotherapy efficacy by limiting cytotoxic immune cell infiltration into malignant regions." (PMID 39516356, 2024). "A recent study showed that macrophage-specific deletion of SPP1 strengthened the efficacy of anti-PD-1 treatment in liver cancer and reduced cancer-associated fibroblasts (CAFs) infiltration and increased cytotoxic T-cell infiltration." (PMID 38919629, 2024). "SPP1, an integrin-binding glycophosphoprotein, has been shown to be associated with immune cell infiltration and found to be upregulated in multiple cancers, including HNSCC." (PMID 38706595, 2024). "Our study has unraveled a unique association between LGMN/SPP1+ TAMs and stemness-related cancer cells (cancer cell cluster C6 marked by co-expression of CD24, CD47 and ICAM1)." (PMID 38169544, 2024). "SPP1 is an extracellular matrix protein expressed in numerous tissues and has been linked to the pathogenesis of malignant tumors, including GBM." (PMID 38491408, 2024). "Cancer-derived SPP1 is linked to MDSC (myeloid-derived suppressor cells) immunosuppression by regulating arginase 1, NOS2, VEGF, and IL-6." (PMID 38491408, 2024). "APOC1+ TAMs also exhibited high expression level of SPP1, a key gene in macrophage polarization linked to poor prognosis for cancer." (PMID 39232806, 2024).
cancer (continued). "Utilizing single-cell sequencing, we dissect the interplay between multiple malignant cell subpopulations and cancer-associated fibroblasts (CAFs), with a special emphasis on SPP1-mediated receptor-ligand interactions." (PMID 39749197, 2024). "Meanwhile, other studies have shown that SPP1 from cancer-associated fibroblasts (CAFs) promotes epithelal-mesenchymal transformation (EMT) through the integrin protein kinase c-α (pkc-α) signaling pathway (RAF)." (PMID 39587675, 2024). "Secreted by cancer-associated fibroblasts, SPP1 enhanced resistance to sorafenib and lenvatinib in HCC." (PMID 39066845, 2024). "The significant increased expression of the SPP1 level is associated with evident hypomethylation of the gene promoter in cancer compared to normal tissues in the TCGA-bladder dataset." (PMID 38067407, 2023). "Most of these genes are expressed in cancer-associated fibroblasts, and SPP1 is mainly expressed in macrophages." (PMID 37188183, 2023). "For instance, higher levels of CHD1L, HDAC1, MUTYH, NEIL3, POLR2L, RUVBL1, and SPP1 expression in cancer cells have been linked to higher levels of drug resistance to nelarabine, acridine, chlorambucil, dexrazoxane, cladribine, and other drugs." (PMID 37923899, 2023). "In general, analyses to detect SPP1 can be categorized into two primary subgroups: enzyme-linked immunosorbent assay (i.e., ELISA) of blood samples and IHC analysis of cancer tissue samples." (PMID 37190178, 2023). "Our study illustrates one mechanism by which GJB2 exerts its cancer-specific relevant effects, that is, causing changes in intercellular communication through the SPP1 signaling pathway." (PMID 37188183, 2023). "GSVA analysis indicated that high-SPP1 group was significantly associated with immune-related pathways such as PD-L1 expression and the PD-1 checkpoint pathway in cancer and the TNF signaling pathway." (PMID 38111044, 2023). "The results showed that the higher expression of miR-146a-5p on upstream of SPP1 is associated with a higher surviving rate in cancer patients." (PMID 36688087, 2023). "It was found that a subpopulation of macrophages with high expression of osteopontin (SPP1), in combination with CAFs (cancer-associated fibroblasts) mediates resistance to immune checkpoint inhibitors." (PMID 38144522, 2023). "Among CD44 variants, CD44v9 is considered to be associated with cancer stem cells in various cancers, but few reports have described the interactions between CD44v9 and SPP1." (PMID 37190178, 2023). "A pan-cancer analysis of SPP1 showed that it promotes immune cell infiltration and that its upregulation is associated with poor prognosis in a variety of cancers." (PMID 37716978, 2023). "We found that the higher expression of miR-146a-5p on upstream of SPP1 is associated with a higher surviving rate in cancer patients." (PMID 36688087, 2023). "A large number of polymorphisms have been identified along the SPP1 gene and some have been associated with cancer and autoimmune diseases such as rheumatoid arthritis, asthma, and inflammatory bowel disease." (PMID 37444590, 2023). "While C1QC+ TAMs preferentially express phagocytosis- and antigen presentation-related genes, SPP1+ TAMs have a proangiogenic signature and are more likely to engage in crosstalk with cancer-associated fibroblasts (CAFs) and endothelial cells." (PMID 37090726, 2023). "To better understand the relevance and underlying mechanism of SPP1 expression in cancer, we evaluated the relationship between immune and stromal scores and SPP1 expression using the CIBERSORT analysis." (PMID 35067176, 2022). "In particular, we demonstrated that the ligand-activated CSF-1R increased the expression of spp1 transcript encoding for osteopontin, a key player in cancer development and metastasis." (PMID 36555673, 2022). "Together, these data indicated that high SPP1 expression was widely associated with immunity in cancers." (PMID 35067176, 2022).
cancer (continued). "In general, analyses for detecting SPP1 can be categorized into two subgroups: enzyme-linked immunosorbent assay (ELISA) of blood samples and immunohistochemistry (IHC) of cancer tissue samples." (PMID 36139536, 2022). "SPP1 is considered to play a cancer-promoting role and is often associated with a worse prognosis in various tumors, but its prognostic significance in iCCA is still controversial." (PMID 35347134, 2022). "We tested if SPP1 expression of TAMs would be associated with the PD-L1 expression of cancer cells and TAMs in this lung cohort." (PMID 36139536, 2022). "Other upregulated genes (e.g., THBS3, SPARC, and SPP1) have also been implicated in cancer cell invasiveness." (PMID 35205840, 2022). "SPP1, whose protein product is known as OPN, is closely associated with tumorigenesis and metastasis in several cancer types." (PMID 35432310, 2022). "Secreted phosphoprotein 1 (SPP1), also known as osteopontin (OPN), is an extracellular matrix protein closely associated with malignant tumors." (PMID 36203528, 2022). "Overall, the landscape of SPP1 SNPs is very complex and, together with alternative splicing variants, can be substantially involved in cancer progression." (PMID 34209679, 2021). "Our current study shows that EMT is the biological process in cancer cells most associated with SPP1+ TAMs as revealed by single-cell analysis, and the potential effect of SPP1+ TAMs on cancer cells is further confirmed by TCGA bulk data." (PMID 34676217, 2021). "Eight genes are in the overlap of all subgroups, among them immune-related genes (DEFB1, AOC1, JCHAIN) as well as genes (215780_s_at/SET, SPP1) that were reported in the literature to be associated with different types of cancer." (PMID 34876106, 2021). "The acquired TIC-like phenotypes of cancer cells were associated with the activation of ITGB1/YBX1/SPP1/NF-κB signaling." (PMID 34758833, 2021). "Numerous studies suggest the importance of SPP1-transcript variant expression in cancer progression and prognosis." (PMID 32503462, 2020). "Further, high levels of SPP1 gene expression were associated with a poor prognosis for these cancers." (PMID 31849319, 2019). "Until now, a few studies had focused on the association of SPP1 SNPs with the susceptibility to some human cancers." (PMID 31921672, 2019). "The elevated SPP1 levels in cancer cells are associated with cellular proliferation, invasion and angiogenesis." (PMID 26857387, 2016). "On one hand, this research shed lights on the relationship of genetic polymorphisms in SPP1 gene and the increased susceptibility to human cancers in Chinese population systematically." (PMID 26267616, 2015). "Several studies have been conducted to examine the associations between osteopontin (OPN) promoter gene SPP1 polymorphisms with human cancers in Chinese population, but the results remain inconsistent." (PMID 26267616, 2015). "The aim of this meta-analysis is to clarify the associations between SPP1 polymorphisms and cancer susceptibility." (PMID 26267616, 2015). "This causes SPP1 to avoid the apoptotic stimulus, one of the “hallmarks of cancer”, which invasive cells will be receiving from this new tissue." (PMID 20805891, 2010). "SPP1, a secreted glycoprotein, also regulates cell adhesion and is well associated with metastasis in various cancers." (PMID 21152079, 2010). "SPP1 (osteopontin), a multifunctional extracellular matrix protein, has been implicated in macrophage recruitment, angiogenesis, and promotion of an immunosuppressive tumor microenvironment in diverse cancers." (PMID 41208987, 2025). "However, some studies have linked SPP1 to tumorigenesis in various cancers, including pancreatic and colorectal cancers, as well as melanoma." (PMID 40141426, 2025).